CYB5RL (cytochrome b5 reductase like)
Description:
Putative NADH-cytochrome b5 reductases family protein. May participate in fatty acid desaturation and elongation, cholesterol biosynthesis, drug metabolism, and, in erythrocyte, methemoglobin reduction.
Synonyms: LOC606495
Tractability: PROTAC: ubiquitination databases record sites on it.
Gene: Protein-coding gene on chromosome 1 (54,169,651 to 54,200,073, reverse strand). Ensembl gene ENSG00000215883.
Subcellular location (Human Protein Atlas): Nucleoplasm
Pathways (Reactome):
Transport of small molecules: Erythrocytes take up carbon dioxide and release oxygen
Gene Ontology:
Molecular function: cytochrome-b5 reductase activity, acting on NAD(P)H; cytochrome-b5 reductase activity, acting on NADH; oxidoreductase activity
Biological process: bicarbonate transport
Cellular component: endoplasmic reticulum membrane
Genetic constraint (gnomAD): Loss-of-function variants: 36 observed, 35.82 expected, observed/expected ratio (o/e) 1, 90% interval 0.77 to 1.33. The upper end of that interval is the gene's LOEUF score, 1.33, which puts it in group 5 of 6, group 1 being the genes least tolerant of losing a copy. Missense variants: 373 observed, 394.29 expected, observed/expected ratio (o/e) 0.95, 90% interval 0.87 to 1.03. Synonymous variants: 133 observed, 151.42 expected, observed/expected ratio (o/e) 0.88, 90% interval 0.76 to 1.01.
Homologues: Orthologues: chimpanzee CYB5RL (99% identical), macaque CYB5RL (96% identical), pig CYB5RL (86% identical), rabbit CYB5RL (83% identical), guinea pig CYB5RL (82% identical), mouse Cyb5rl (78% identical), rat Cyb5rl (76% identical), dog CYB5RL (72% identical), Drosophila melanogaster CG7914 (21% identical). Paralogues in human: CYB5R4 (27% identical), CYB5R1 (26% identical), CYB5R3 (25% identical), CYB5R2 (23% identical), OXNAD1 (17% identical).